STC1 (stanniocalcin 1)
Diseases named in the same sentence as STC1 in open-access papers (continued):
Sharing a sentence is not in itself a finding about the gene and the disease.
breast carcinoma (continued). "Whether activated MAPK signaling in lung metastatic breast cancer cells is an initiating factor for STC1 upregulation is worthy of investigation." (PMID 37400459, 2023). "This study found that the high expression of STC1 in tumor tissue was associated with poor LMFS in breast cancer patients, which has not been reported by previous works." (PMID 37400459, 2023). "We found that the functions of STC1 in breast cancer cells are mediated by S100A4." (PMID 37400459, 2023). "This indicates that breast cancer cell-derived STC1 mainly acts on tumor cells themselves." (PMID 37400459, 2023). "Overall, our findings reveal that STC1 plays important role in breast cancer lung metastasis." (PMID 37400459, 2023). "On the one hand, high STC1 expression was correlated with poor clinical outcomes in breast cancer." (PMID 35927233, 2022). "Another study demonstrated that STC1 can promote the invasion of breast cancer cells." (PMID 35607443, 2022). "It is noteworthy that the roles of STC1 are intricate in OC and breast cancer." (PMID 35273656, 2022). "STC1 is related to chemoresistance, invasion, and metastasis in breast cancer." (PMID 36344487, 2022). "Through modulation of STC1 expression in different breast cancer cell lines, our study found that STC1 could promote the proliferation and growth of breast cancer cells and promote metastasis." (PMID 34722511, 2021). "Collectively, our results suggest that STC1 promotes tumorigenesis in breast cancer and that breast cancer patients with a high expression of STC1 are more resistant to treatment, potentially through promotion of the HR pathway, and therefore have worse survival." (PMID 34722511, 2021). "Moreover, STC1 silencing sensitized breast cancer cells to treatment with irradiation (IR), olaparib, or cisplatin in vitro." (PMID 34722511, 2021). "STC1 also promotes HR and may lead to resistance to DNA damage-inducing drugs, thereby leading to poor survival in breast cancer patients." (PMID 34722511, 2021). "Mccudden et al58 showed that STC1 and its receptor were colocalized in 91% of examined human breast cancer biopsies (53/58) by immunocytochemistry and in situ ligand and binding staining, and all cancerous cells were positively stained for both the ligand and receptor." (PMID 32468698, 2020). "Of these, genes hypothesized to have a tumor-suppressor function included LINC00886, MAN2C1, SNUPN, and STC1, while YBEY, SEMA4A, and MUTYH may have an oncogenic role in breast carcinogenesis based on their associations with breast cancer risk." (PMID 32139696, 2020). "Moreover, STC1 expression is suppressed by PKCα (protein kinase Cα), a highly expressed protein in breast cancers." (PMID 32468698, 2020). "For example, the elevated expression of STC1 is discovered in breast carcinomas and ovarian cancer, which means STC1 may act as a carcinogenesis factor." (PMID 33072314, 2020). "Increased STC1 expression has been observed in many types of cancer, including colorectal cancer, hepatocellular carcinoma, non-small cell lung cancer, ovarian cancer, breast carcinoma and leukemia." (PMID 25740019, 2015). "STC1 also appears to be involved in human carcinogenesis, including colon and breast cancers." (PMID 22200953, 2012). "However, in some highly heterogeneous tumors, such as breast cancer, STC1 may be differentially expressed in different tumor subtypes and sizes, which may be affected by the copy number variations, gene expression profile of different tumor subtypes." (PMID 39654892, 2024). "Additionally, evidence showed that the high expression of STC1 could promote self-renewal ability and maintain the stem-like characteristics of breast cancer stem cells." (PMID 37004088, 2023). "Furthermore, we queried the association between STC1 expression and lung metastasis in a combined breast cancer microarray data set (GSE2034, GSE2604, and GSE5327) and found that the high STC1 expression was significantly associated with lower LMFS in breast cancer patients." (PMID 37400459, 2023).
breast carcinoma (continued). "Therefore, the involvement of S100A4 may convincingly explain the multifunctional regulatory effect of STC1 on breast cancer cells themselves and the tumor microenvironment of breast cancer lung metastases." (PMID 37400459, 2023). "Importantly, S100A4 knockdown diminishes STC1-induced lung metastasis of breast cancer." (PMID 37400459, 2023). "Furthermore, combined treatment with STC1 inhibition and DNA damage-inducing drugs may be a novel strategy to improve the outcome of patients with STC1-expressing breast cancer." (PMID 34722511, 2021). "Since TNBC has been reported to harbor a high probability of BRCA1 deficiency and a homologous recombination defect (HRD), we hypothesized that STC1 has an important role in DNA repair and can be used as a biomarker for DNA damage-inducing agents in breast cancer." (PMID 34722511, 2021). "However, the function of STC1 in breast cancer is still elusive." (PMID 34722511, 2021). "Furthermore, combining STC1 inhibition and DNA damage-inducing drugs may be a novel approach to improve the survival of patients with STC1-expressing breast cancer." (PMID 34722511, 2021). "However, the effect of STC1 on cell proliferation in breast cancer depends on the subtype." (PMID 32468698, 2020). "Therefore, a much higher level of STC1 in breast cancer patients may indicate a more invasive subtype and worse prognosis." (PMID 32468698, 2020). "Additionally, we previously demonstrated that CAPG could bind to STC-1 promoter region (-451 bp to -75 bp) to activate STC-1 transcription and substantially promote breast cancer metastasis." (PMID 31660072, 2019). "Stanniocalcin 1 (STC1), a glycoprotein found in the endocrine glands of fish kidney, has enhanced expression in HCC, ovarian cancer, breast cancer, and GB." (PMID 39957375, 2025). "The relationship between STC-1 and cancer has become a focus of research, with elevated expression of STC-1 observed in various cancers, including breast cancer, lung cancer, and ovarian cancer." (PMID 39071498, 2024). "We noticed that the knockdown of S100A4 restored the promotional action of STC1-overexpressing breast cancer cells on these functions, and overexpression of S100A4 rescued the inhibitory effect of STC1 knockdown breast cancer cells on these functions." (PMID 37400459, 2023). "According to previous studies, STC1 can activate PI3K/AKT and JNK/c-Jun signaling pathways to enhance the invasiveness of breast cancer cells." (PMID 37400459, 2023). "We also found that in breast cancer cells with lung-tropism, activated JNK signaling upregulates STC1 expression." (PMID 37400459, 2023). "DROSHA RNase III was upregulated in a number of cancers and interacted with β-catenin to activate stanniocalcin 1 (STC1) in an RNA cleavage-independent manner, which in turn contributed to the properties of breast cancer stem-like cells (BCSCs)." (PMID 35721510, 2022). "IHC evaluation of breast cancer specimens demonstrated that a high expression of STC1 was negatively correlated with recurrence-free survival in breast cancer, indicating that STC1 expression could be used as a predictive marker for a poor prognosis in breast cancer." (PMID 34722511, 2021). "In addition, immunohistochemical staining of breast cancer specimens showed that a high expression of STC1 was negatively correlated with recurrence-free survival in breast cancer, indicating that STC1 expression could be used as a predictive marker for a poor prognosis in breast cancer." (PMID 34722511, 2021). "The expression of STC1 mRNA has been widely investigated as a biomarker for cancer dissemination in HCC, breast cancer, and melanoma." (PMID 22200953, 2012). "One study suggested that STC1 was positively regulated by desumoylated progesterone receptor in the absence of ligand for the breast cancer cells." (PMID 35273656, 2022).
breast carcinoma (continued). "Furthermore, elevated STC-1 has been shown to augment cellular invasion and metastasis through the JNK/c-Jun-dependent signaling pathway in breast cancer, ovarian cancer, and gliomas." (PMID 34650342, 2021). "Therefore, we chose the breast cancer cell lines MCF-7 and ZR7530 for experiments on the overexpression of STC1 and the 231 and 231 HM cell lines for STC1-silencing experiments." (PMID 34722511, 2021). "STC1 and MMP1 have been regarded as promising markers for breast cancer; therefore, the regulation in the study, although it was in normal mammary epithelial cells, might provide reference for the targeted therapeutic treatment of breast cancer." (PMID 33946970, 2021). "In breast cancer, BRCA1 gene may induce STC1 to express; STC1 and STC2 in tumor tissues indicate over expression in ER+ breast cancer cells, hormones is an essential element to regulate the expression of STC2." (PMID 37287492, 2021). "In the context of tumor-TME interactions, STC1 was reported as being upregulated in breast cancer-educated fibroblasts, but no in vivo effects of fibroblast-derived STC1 in co-xenotransplantation experiments were identified." (PMID 32579928, 2020). "Nevertheless, the complete function and significance of STC1 in breast cancer is not yet clear and needs further investigation." (PMID 32468698, 2020). "High expression of STC1 was frequently detected in human tumor samples of hepatocellular carcinoma (HCC), colorectal cancer, lung adenocarcinoma, breast cancer and thyroid carcinomas, however, low expression of STC1 was found in tumor-derived ovarian epithelial cells." (PMID 28545028, 2017). "Subsequently, studies in breast cancer and PDAC also spotted that STC1 could be secreted by CAFs." (PMID 37004088, 2023). "However, the mechanism responsible for STC1 promotion of breast cancer metastasis to the lungs has not yet been examined." (PMID 37400459, 2023). "However, multivariate Cox analysis revealed that STC1 was not an independent prognostic factor for breast cancer (p > 0.05)." (PMID 34722511, 2021). "Although the immunostaining of breast cancer lung metastases showed no change in the number of α-SMA-positive cells after STC1 manipulation, the immunostaining of α-SMA may not reflect the activation of lung fibroblasts because of the extremely abundant fibroblasts in the lungs." (PMID 37400459, 2023). "In addition, it was observed that silencing STC1 expression reduced tumor growth in both murine and human breast cancer cells in vivo, but no obvious effects on proliferation were observed in either model in vitro, implying that the cell microenvironment is important for STC1 function." (PMID 34722511, 2021).
ovarian carcinoma (46 papers, 2011 to 2025). A malignant neoplasm originating from the surface ovarian epithelium. "Another gene, STC1, plays a role in promoting tumor metastasis in ovarian cancer, and the lipid metabolism and cisplatin resistance of tumor cells are also associated with STC1." (PMID 40295497, 2025). "This also applies to hormone-dependent tumor tissues like breast and ovarian cancers underlying the role of STC-1, especially in adenocarcinoma development." (PMID 34650342, 2021). "Many laboratory experiments have revealed that STC1 expression was associated with tumorigenesis in renal, breast and ovarian cancers." (PMID 29467934, 2018). "STC1 overexpression has been linked with increased proliferation, migration and colony formation in human ovarian cancer cell lines as well as increased expression of cell cycle regulation proteins and increased expression of anti-apoptotic proteins, hindering apoptosis." (PMID 34867818, 2021). "Emerging evidences have revealed that STC1 is implicated in carcinogenesis and the progression of mangy types of cancer, including but not limited to colorectal, breast, hepatocellular carcinoma, cervical, and ovarian cancer." (PMID 31889892, 2019). "Previous studies have confirmed that STC1 promotes metastasis through EMT activation in ovarian cancer and enhances cell survival via NF‐κB signaling in cervical cancer." (PMID 41020346, 2025). "In previous studies, overexpression of STC1 stimulated the development of EMT in ovarian cancer cells, thereby promoting cancer cell metastasis." (PMID 41020346, 2025). "In ovarian cancer, stanniocalcin 1 enhances metastatic capacity, lipid metabolism, and cisplatin resistance through the FOXC2/ITGB6 signaling pathway." (PMID 40746552, 2025). "Consistent with ovarian cancer, in lung adenocarcinoma and clear renal cell carcinoma, high expression of STC1 had also been shown to regulate the levels of cell cycle proteins and apoptotic proteins, thereby facilitating cell proliferation." (PMID 39654892, 2024). "In ovarian cancer, STC1 stimulated high expression of cell cycle-related proteins (cyclin A/B1/D1 and CDK2/4) for rapid proliferation of tumor cells and mitotic cycle of G1 to S was dramatically shortened." (PMID 38215156, 2024). "Our results demonstrated that ovarian cancer, lung cancer, and ovarian epithelial tumors shared a relatively high alteration frequency of STC1." (PMID 39201771, 2024). "For example, STC1 promotes ovarian cancer metastasis, lipid metabolism, and DDP chemotherapy resistance through the FOXC2/ITGB6 signalling pathway." (PMID 38556542, 2024). "We found that STC1 is up-regulated in chronic lymphocytic leukemia, acute myeloid leukemia, myeloma, diffuse large B-cell lymphoma, ovarian cancer, and lung cancer." (PMID 39201771, 2024). "This study is aimed at evaluating serum autoantibodies against four tumor-associated antigens, including LRDD, STC1, FOXA1, and EDNRB, as biomarkers in the immunodiagnosis of ovarian cancer (OC)." (PMID 35273656, 2022). "For instance, STC1 was shown to inhibit the proliferation of cervical cancer cells but promote tumor proliferation and cell colony formation in ovarian cancer, indicating that the effects of STC1 vary among different cancers." (PMID 34722511, 2021). "The higher expression levels of STC1 in human cancer tissues were documented, although some exceptional cases in breast and ovarian cancers were reported." (PMID 33156861, 2020). "Some previous studies have found that STC1 expression down‐regulates after loss‐of‐function of BRCA1, which leads to breast and ovarian cancer." (PMID 32468698, 2020). "In summary, for the first time, our data demonstrate sevoflurane inhibits cell proliferation, migration and invasion and induces cell cycle arrest and apoptosis in ovarian cancer cells through targeting STC1." (PMID 31889892, 2019).
ovarian carcinoma (continued). "The anti-apoptotic effect of STC1 was reported in different cell models, including thapsigargin-treated Paju cells, hypoxia-induced lung cancer cells, and in human ovarian cancer cells." (PMID 26469082, 2015). "A considerable number of studies demonstrate that STC1 promotes tumor migration and invasion, with the exception of two studies in breast and ovarian cancer." (PMID 24743310, 2014). "In this study, we examined a previously known HIF-1alpha target gene, Stanniocalcin 1 (STC1), which has been shown to be a secreted oncogene in ovarian cancer." (PMID 24348907, 2013). "The only published study on human circulating STC1 level has reported significantly increased serum STC1 in ovarian cancer patients." (PMID 23145134, 2012). "In contrast to the inhibitory effect of STC1 on the transendothelial migration, STC1 exerted a promigratory effect on human ovarian cancer cells." (PMID 22069492, 2011). "STC1 was altered in 14.55% of 110 cases (Deep Deletion was 14.55%) in ovarian cancer, 13.16% of 38 cases (Amplification was 5.26%, Deep Deletion was 7.89%) in lung cancer, and 7.36% of 584 cases (Mutation was 0.34%, Amplification was 0.17%, Deep Deletion was 6.85%) in the ovarian epithelial tumor." (PMID 39201771, 2024). "Stanniocalcin 1 (STC1) plays an integral role in ovarian cancer (OC)." (PMID 35392966, 2022). "In addition to leukemia cells, STC‐1 expression has been found to be increased in various cancers such as colorectal cancer and ovarian cancer." (PMID 33826244, 2021). "It was pointed out in the literature that STC1 affected the occurrence and development of ovarian cancer, and could activate phosphorylation of Akt thereby affecting epithelial-mesenchymal transition (EMT)." (PMID 33644060, 2021). "However, this is the opposite view from recent studies showing that STC1 is overexpressed in breast and ovarian cancer tissues compared normal tissues." (PMID 32468698, 2020). "We suspected that STC1 may be involved the effect of sevoflurane on proliferation, migration and invasion of ovarian cancer cells." (PMID 31889892, 2019). "STC1 has been revealed to be up-regulated in ovarian cancer and involved in tumor progression." (PMID 31889892, 2019). "Increased STC1 gene expression has been found in hepatocellular, colorectal, acute leukemia, and medullary thyroid carcinomas, however, decreased expression of STC1 expression was found in breast and ovarian cancer cell lines." (PMID 23382863, 2013). "Aberrant STC-1 expression has been reported in breast and ovarian cancers." (PMID 21672207, 2011). "However, a recent study showed that over-expression of STC-1 in ovarian cancer cells enhanced cell proliferation, migration, and tube formation in vitro and increased the growth of xenograft tumors in mice." (PMID 21672207, 2011). "Recently, it has been discovered that STC1 is expressed in high levels in ovarian cancer cell lines and ovarian cancer tissues, leading to increased anti-apoptotic proteins and cell cycle regulatory proteins in normal or malignant ovarian cells that have overexpressed STC1." (PMID 40741411, 2025). "Additionally, the correlation between STC1 expression and breast/ovarian cancer is intricate." (PMID 32468698, 2020). "Moreover, knockdown of STC1 could arrest cell cycle in G0/G1 phase and promote apoptosis in SKOV3 cells, suggesting an oncogenic role of STC1 in ovarian cancer." (PMID 31889892, 2019). "Various cancers overexpress STC1, and STC1 promotes chemoresistance to cisplatin by directly binding to αvβ6 integrin to activate the PI3K signaling pathway in ovarian cancer cell lines Skov3-ip1 and Hey." (PMID 40243917, 2025). "In this prospective, longitudinal study of 107 women with ovarian cancer and ascites accumulation, we determined corresponding serum and ascites levels of IGF-1, IGF-2, PAPP-A, PAPP-A2, STC1, and STC2 and assessed their relationship with mortality." (PMID 38396692, 2024).